NOP10 (NOP10 ribonucleoprotein)
Description:
Required for ribosome biogenesis and telomere maintenance. Part of the H/ACA small nucleolar ribonucleoprotein (H/ACA snoRNP) complex, which catalyzes pseudouridylation of rRNA. This involves the isomerization of uridine such that the ribose is subsequently attached to C5, instead of the normal N1. Each rRNA can contain up to 100 pseudouridine ('psi') residues, which may serve to stabilize the conformation of rRNAs. May also be required for correct processing or intranuclear trafficking of TERC, the RNA component of the telomerase reverse transcriptase (TERT) holoenzyme.
Synonyms: NOLA3; NOP10P; MGC70651; CHINE2; DKCB1; PFBMFT9
Tractability: PROTAC: ubiquitination databases record sites on it; its protein half-life has been measured.
Gene: Protein-coding gene on chromosome 15 (34,339,159 to 34,343,180, reverse strand). Ensembl gene ENSG00000182117.
Subcellular location: Nucleus, nucleolus; Nucleus, Cajal body
Subcellular location (Human Protein Atlas): Nuclear bodies
Pathways (Reactome):
Cell Cycle: Telomere Extension By Telomerase
Metabolism of RNA: rRNA modification in the nucleus and cytosol
Gene Ontology:
Molecular function: box H/ACA snoRNA binding; protein binding; RNA binding; telomerase RNA binding; snoRNA binding
Biological process: telomerase RNA localization to Cajal body; telomere maintenance via telomerase; pseudouridine synthesis; rRNA pseudouridine synthesis; snRNA pseudouridine synthesis; ribosome biogenesis; snoRNA guided rRNA pseudouridine synthesis
Cellular component: box H/ACA snoRNP complex; box H/ACA telomerase RNP complex; nuclear body; telomerase holoenzyme complex; box H/ACA scaRNP complex; nucleoplasm; sno(s)RNA-containing ribonucleoprotein complex; Cajal body; nucleolus
Genetic constraint (gnomAD): Loss-of-function variants: 6 observed, 9.73 expected, observed/expected ratio (o/e) 0.62, 90% interval 0.34 to 1.22. That is too few expected variants to judge how well the gene tolerates losing a copy. Missense variants: 75 observed, 87.14 expected, observed/expected ratio (o/e) 0.86, 90% interval 0.71 to 1.04. Synonymous variants: 28 observed, 32.87 expected, observed/expected ratio (o/e) 0.85, 90% interval 0.63 to 1.17.
Gene-disease validity (ClinGen):
ClinGen rates the evidence that NOP10 causes each of these diseases.
pulmonary fibrosis and/or bone marrow failure syndrome, telomere-related, 9 (autosomal dominant): Limited.
Homologues: Orthologues: chimpanzee NOP10 (100% identical), mouse Nop10 (100% identical), rat Nop10 (100% identical), guinea pig NOP10 (98% identical), macaque NOP10 (98% identical), dog NOP10 (97% identical), pig NOP10 (97% identical), rat Nop10l1 (89% identical), zebrafish nop10 (81% identical), tropical clawed frog nop10 (77% identical), Drosophila melanogaster Nop10 (66% identical), Caenorhabditis elegans nola-3 (59% identical).
Diseases named in the same sentence as NOP10 in open-access papers:
NOP10 is named in the same sentence as 31 diseases in open-access papers, as found by Europe PMC text mining. Sharing a sentence is not in itself a finding about the gene and the disease. The quoted sentences say what the papers report.
dyskeratosis congenita (8 papers, 2010 to 2021). Dyskeratosis congenita (DC) is a rare ectodermal dysplasia that often presents with the classic triad of nail dysplasia, skin pigmentary changes, and oral leukoplakia associated with a high risk of bone marrow failure (BMF) and cancer. "Mutations in the Dkc1, Nhp2, and Nop10 genes have been linked to dyskeratosis congenita (DC), a rare but fatal human genetic disorder that impairs stem cell function and proliferation generally attributed to defects in telomerase or ribosome biogenesis." (PMID 25407680, 2014). "Another genetic disease, known as dyskeratosis congenita (DKC), occurs due to mutations in a couple of genes encoding proteins that localize to CBs (e.g., EST1A, NHP2, NOP10, and WRAP53), and resulting in defective ribosome biogenesis and telomere maintenance." (PMID 32764415, 2020). "Autosomal forms of Dyskeratosis Congenita can derive from mutations of NOLA2 or NOLA3 encoding for NHP2 and NOP10, respectively." (PMID 29874862, 2018). "For instance, dyskeratosis congenita (DKC), a syndrome characterized by a classic triad of nail dysplasia, skin pigmentary changes, oral leukoplakia, and bone marrow failure, is associated with short telomeres and mutations in TCAB1, dyskerin, NHP2, and NOP10." (PMID 27240403, 2016). "Individuals with dyskeratosis congenita (DC), a cancer susceptibility and inherited bone marrow failure syndrome (IBMFS), have mutations in genes important in telomere biology, including DKC1, TERC, TERT, TINF2, NHP2 and NOP10." (PMID 21113082, 2010).
breast carcinoma (3 papers, 2017 to 2024). "The association between NOP10 mRNA and aggressive features of the tumour were also demonstrated and confirmed in the Breast Cancer Gene Expression Miner v4.3 database." (PMID 33161513, 2021). "For instance, RELA-bound genes such as NOP10, a member of the H/ACA small nucleolar RNP (snoRNP) gene family, and TPI1, an important glycolytic enzyme are associated with poor prognosis in breast cancer." (PMID 39418101, 2024). "NOP10 expression was assessed at mRNA level employing the Molecular Taxonomy of Breast Cancer International Consortium (METABRIC) (n = 1980) and Cancer Genome Atlas (TCGA) BC cohorts (n = 854)." (PMID 33161513, 2021). "We selected four genes (NOP10, OST4, SNRPG, TOMM7) known to be present in EVs from MCF-7 breast cancer cells overexpressing Rab27b-GFP11." (PMID 28577337, 2017).
lung carcinoma (3 papers, 2021 to 2025). "However, the upregulation of NOP10, a vital part of the H/ACA snoRNP complex, has been linked to poorer outcome of lung cancer patients and its depletion resulted in the decreased level of a few snoRNAs including SNORA65, leading to impaired tumor growth." (PMID 36585466, 2022). "Thus, our results indicate that NOP10 is required for proliferation, migration, and invasion of lung cancer cells." (PMID 33288886, 2021). "We identified, that increased expression of the H/ACA box protein NOP10 was associated with a poor prognosis of NSCLC patients and its deletion inhibited cell growth, proliferation, migration, and invasion of lung cancer cells via dysregulation of SNORA65, SNORA7A, and SNORA7B." (PMID 33288886, 2021). "In vitro, NOP10 suppression could inhibit cell growth, proliferation, and tumorigenicity of lung cancer cell lines." (PMID 33288886, 2021).
chronic lymphocytic leukaemia (2 papers, 2021 to 2022). "Expression of protein encoding gene NOP10 has been reported to be decreased in patients with chronic lymphocytic leukaemia (CLL)." (PMID 35054812, 2022).
non-small cell lung carcinoma (2 papers, 2022 to 2025). A group of at least three distinct histological types of lung cancer, including non-small cell squamous cell carcinoma, adenocarcinoma, and large cell carcinoma. "In non-small cell lung cancer (NSCLC), increased expression of NOP10 correlates with enhanced cellular proliferation and migratory capacity." (PMID 39871386, 2025). "The link between the upregulation of H/ACA snoRNAs and poor prognosis was also observed in the case of non-small cell lung cancer, where expression of the H/ACA snoRNA binding protein Nop10 was found to drive tumorigenesis." (PMID 35047824, 2022).
pulmonary fibrosis (2 papers, 2025). Chronic progressive interstitial lung disorder characterized by the replacement of the lung tissue by connective tissue, leading to progressive dyspnea, respiratory failure, or right heart failure. "This resulted in the exclusion of well-defined monogenic pulmonary fibrosis genes, such as ABCA3 or NOP10, which show recessive inheritance." (PMID 40311650, 2025).
bone marrow failure syndrome (1 paper, 2025). "Additionally, patients with ITGV-BMFs may have abnormalities in telomere biology, including critically short telomere and germline variants in gene such as TERT or NOP10, which are linked to inherited bone marrow failure syndromes." (PMID 40574285, 2025).
cyst (1 paper, 2023). A sac-like closed membranous structure that may be empty or contain fluid or amorphous material. "To test this, we depleted Nop60B and Nop10 in the cysts by RNAi using a bamGAL4 driver, which is active in the 2- to 8-cell cyst stages." (PMID 37343092, 2023).
lung adenocarcinoma (1 paper, 2023). A carcinoma that arises from the lung and is characterized by the presence of malignant glandular epithelial cells. "Furthermore, low expression levels of the other RNP core protein components NHP2, NOP10, and GAR1 were also associated with poor prognosis levels in lung SCC and ovarian cancer, but not in lung adenocarcinoma or HNSCC." (PMID 36732018, 2023).
melanoma (1 paper, 2022). A malignant, usually aggressive tumor composed of atypical, neoplastic melanocytes. "From our list of prioritized variants and genes, three genes (MYO7A, WRN and NOP10) warrant a more detailed discussion, due to gene function and previous associations with melanoma." (PMID 35085295, 2022).
metastatic disease (1 paper, 2021). "We propose to include NOP10 immunostaining within the current battery of markers for stratifying PPGL patients to fine-tune their prognosis, thereby providing early detection of metastatic disease and ultimately bettering the planning of treatment options." (PMID 34638246, 2021).
uterine corpus endometrial carcinoma (1 paper, 2023). A endometrial carcinoma (disease) that involves the body of uterus. "Using a series of 543 uterine corpus endometrial carcinoma (UCEC) issued from the TCGA database, a significant association was observed for NHP2 (P = 0.0003) and TAF1B (P = 0.034), but not for Nop10 (P = 0.77), − high levels of NHP2 and TAF1B being associated with the poorest outcome." (PMID 36370117, 2023).
Viral infection (1 paper, 2021). "Viral infection upregulated another host factor for pseudouridine, NOP10, observed in one of six experiments." (PMID 34502037, 2021).
cancer (8 papers, 2021 to 2025). A tumor composed of atypical neoplastic, often pleomorphic cells that invade other tissues. "The role of telomerase in cancer was reviewed recently.Telomerase is associated with a set of accessory proteins, including dyskerin and nucleolar protein 10 (NOP10)." (PMID 35565379, 2022). "Mutations in NOP10 gene have been implicated in various forms of DC but their role in cancer is less established." (PMID 33599797, 2021). "The seven hub RBPs CD3EAP, POP5, NOP10, ATXN1, ZC3H12C, RBPMS, and SBDS were implicated in the progression and prognosis of many cancers." (PMID 36262474, 2022). "Recently, the aberrant expression pattern of DKC1, NHP2, and NOP10 in several cancer entities has been reviewed." (PMID 33803145, 2021). "Differential expression and pathway enrichment analyses revealed that NOP10- and NHP2-positive PTCs are enriched in pathways critical to cancer biology, including DNA repair, mTORC1 signaling, oxidative phosphorylation, hypoxia, and ROS response." (PMID 41357133, 2025). "Conversely, silencing NOP10 significantly reduces the expression of SNORA65, SNORA7A, and SNORA7B, as well as suppressing cancer cell proliferation and migration, ultimately decreasing TERC levels." (PMID 39871386, 2025).
tumor (8 papers, 2017 to 2025). "Again, Nop10 protein expression was predominantly detected in the nucleus and nucleolus of invasive tumor cells, demonstrating a notable association with aggressive characteristics." (PMID 39821858, 2025). "The MIF pathway, in particular, has been implicated in tumor inflammation and immune evasion, and its activation in NOP10+/NHP2+ PTCs may facilitate cross-talk with macrophages and T cells, contributing to an immunosuppressive niche in the ccRCC TME." (PMID 41357133, 2025). "High NOP10 mRNA expression was significantly associated with features characteristic of poor prognosis including younger age, higher tumour grade, poorer NPI scores, hormone receptor negativity, HER2 positivity, TNBC phenotype (all p < 0.0001) and advance nodal stage (p = 0.001)." (PMID 33161513, 2021). "Pie chart analysis illustrated a progressive reduction in the proportion of NHP2- and NOP10-positive tumor cells across cell states, supporting these mechanistic insights, and overall ratios were similar between the two markers." (PMID 41357133, 2025). "Specifically, we reveal how PTCs with telomerase-associated genes, like NOP10 and NHP2 dynamically modulate cellular senescence and interact with the tumor microenvironment." (PMID 41357133, 2025). "During tumor evolution, telomerase reactivation—possibly modulated by NOP10 and NHP2—enables cells to evade senescence and acquire malignant traits." (PMID 41357133, 2025). "scRNA-seq revealed that proximal tubule cells (PTCs) with telomerase-associated genes NOP10 and NHP2 exhibited complex senescence dynamics, characterizing distinct cellular communication patterns in the tumor microenvironment." (PMID 41357133, 2025). "We identified a significant upregulation of NOP10 protein in NSCLC tumor tissue compared to matched normal controls in the adenocarcinoma as well as in the squamous subtype." (PMID 33288886, 2021). "In multivariate Cox regression models including other prognostic covariates (tumour size, grade and nodal stage), NOP10 mRNA was an independent predictor of shorter BCSS (p = 0.04, HR 1.3, 95% CI = 1.0–1.7)." (PMID 33161513, 2021). "NOP10 protein expression was significantly associated with shorter DMFS and BCSS in TNBC, while mRNA predicted poor outcome in HER2+ tumours." (PMID 33161513, 2021). "Hence, the observed anti-GBM action by BA could be attributed, to a greater or lesser extent, to its tumor-suppressing potency associated with GFAP, Ki67, Nop10, and H2AX expressions." (PMID 39821858, 2025). "High abundance of NOP10 protein whether in the nucleus or in the nucleoli demonstrated a significant association with unfavourable characteristics including high tumour grade, thus substantiating this hypothesis for non-significance in our study." (PMID 35054812, 2022). "Such discrepancies might be attributed to the differences in the number of cases in each subtype between the Nottingham and METABRIC cohorts or might be due to tumour-specific differences in NOP10 mRNA/protein stability or post-transcriptional regulation of NOP10 expression." (PMID 33161513, 2021). "In the immunofluorescence examination, severe intracytoplasmic Nop10 and H2AX expressions were found in neurons around the tumor mass." (PMID 39821858, 2025). "In the immunofluorescence examination, severe intracytoplasmic Nop10 and H2AX expressions were detected around the tumor mass." (PMID 39821858, 2025). "In the immunofluorescence examination, moderate Nop10 and H2AX expressions were identified in neurons around the tumor mass in B2 group." (PMID 39821858, 2025). "The global communication networks further highlight strong interaction strengths between NOP10+/NHP2+ PTCs and these microenvironmental cell types, reinforcing the notion that these populations are actively engaged in shaping the tumor milieu." (PMID 41357133, 2025). "Compared to normal samples, ATXN1, RBPMS, SBDS, and ZC3H12C were downregulated, and CD3EAP, NOP10, and POP5 were upregulated in UCEC tumor samples." (PMID 36262474, 2022).
tumor (continued). "CD3EAP, NOP10, and POP5 were significantly up-regulated in tumor tissue samples, while ATXN1, RBPMS, SBDS, and ZC3H12C were significantly downregulated in tumor tissue samples calculating by DESeq2 and edgeR, which were consistent with our previous results." (PMID 36262474, 2022). "In chemotherapy- treated patients, high NOP10 protein expression was significantly associated with shorter survival (p = 0.03) and was predictive of higher risk of death (p = 0.028) and development of distant metastasis (p = 0.02) independent of tumour size, nodal stage and tumour grade." (PMID 33161513, 2021). "Additionally, mild intracytoplasmic Nop10 and H2AX expressions were observed in neurons around the tumor mass in brain tissues." (PMID 39821858, 2025). "The findings presented in the current study also demonstrate a dose-dependent reduction in Ki67, Nop10, and H2AX expressions in tumor cells around blood vessels, alongside GFAP expression, following treatment with BA in astrocytes surrounding the tumors in rat GBM model." (PMID 39821858, 2025). "NOP10 protein expression was observed mainly in the nucleus and nucleolus of invasive tumour cells, with expression levels varying from negative to strong." (PMID 33161513, 2021).
genetic disorder (2 papers, 2014 to 2020). "Mutations in PARN, dyskerin or NOP10 cause severe genetic disorders, emphasizing the functional significance of these telomerase subunits and RNA maturation mechanisms." (PMID 33095156, 2020).
NOP10 also shares sentences with these, for which no sentence is quoted: acute myeloid leukaemia (1 paper); adenocarcinoma (1); colorectal cancer (1); Dubowitz syndrome (1); endometrial cancer (1); gastric cancer (1); glioblastoma (1); idiopathic pulmonary fibrosis (1); invasive breast carcinoma (1); liver cancer (1); monoclonal gammopathy of undetermined significance (1); myeloma (1); ovarian carcinoma (1); plasma cell disorders (1); plasma cell leukemia (1).